RN7SKP289 (RN7SK pseudogene 289)
Gene: Miscellaneous RNA gene on chromosome 12 (53,816,185 to 53,816,479, forward strand). Ensembl gene ENSG00000253053.
Homologues: Orthologues: chimpanzee 7SK (98% identical). Paralogues in human: RN7SKP184 (59% identical), RN7SKP44 (59% identical), RN7SKP25 (58% identical), RN7SKP222 (57% identical), RN7SKP189 (57% identical), 7SK (57% identical), RN7SKP203 (57% identical), RN7SKP251 (57% identical), RN7SKP269 (56% identical), RN7SKP87 (56% identical), RN7SKP118 (56% identical), RN7SKP15 (56% identical), and 284 more.